IGF1R (insulin like growth factor 1 receptor)
Diseases named in the same sentence as IGF1R in open-access papers (continued):
Sharing a sentence is not in itself a finding about the gene and the disease.
cancer (continued). "IGF-1 induces the EMT in most cancer cells, whereas IGF-1R activation leads to downregulation of E-cadherin and upregulation of N-cadherin, vimentin, and fibronectin." (PMID 30111747, 2018). "Second, we wished to contribute to an understanding of the control of IGF1R expression because of the receptor’s important role in cancer biology." (PMID 29644076, 2018). "A growing body of evidence indicates that the IGF-1/IGF-1R signaling pathway is a key player in BC cell therapy resistance and cancer recurrence." (PMID 30111747, 2018). "Based on the reported role of IGF1R as a major driver of cancer development and progression, several pharmacological inhibitors were developed including the small-molecule inhibitor OSI-906, which can block both IGF1R and IR." (PMID 29731738, 2018). "The insulin-like growth factor-1 receptor (IGF-1R) has become a potential therapeutic target for cancer." (PMID 29786660, 2018). "The potential role of IGF-1/IGF-1R signaling in cancer progression has been investigated also in lung cancer (LC)." (PMID 30111747, 2018). "IGF-1 is a growth factor which can stimulate the proliferation of cancer cells dramatically, and IGF-1R is highly expressed in PC12 cells." (PMID 30213025, 2018). "Our results provide preclinical evidence for the use of LL28 as a dual IGF1R/Src-targeting drug in cancer therapy." (PMID 29455661, 2018). "It has been reported that the high frequency of IGF1R (39–84%) was detected in patients with various cancers, however, further study is needed to determine the explicit proportion of high IGF1R expression patients among those having TKIs resistance." (PMID 29455669, 2018). "Insulin/IGF-1R signaling is one of the signaling pathways that govern the sensitization of cancer cells to gemcitabine." (PMID 29475434, 2018). "Evidence has been presented showing that the IGF1R promoter constitutes a target to a number of aberrant transcription factors that result from recurrent, cancer-specific chromosomal translocations." (PMID 29455671, 2018). "Evidence suggests that IGF1R and its ligands are involved in the development and progression of cancer." (PMID 30013477, 2018). "IGF1R is considered an attractive target in oncology;33 however, years of clinical research yielded only modest efficacy in cancer patients treated with a single agent of anti-IGF1R therapies." (PMID 30237504, 2018). "Pieces of evidence have indicated that the activated IGF-1R translocates to the nuclei of several human cancer cells and regulates, by acting as a transcription regulator, cancer cell migration through the modulation of MMP-2 expression." (PMID 29690502, 2018). "There are contradictory reports on the relationship of IGF1R and acquired resistance in many human cancers." (PMID 29642855, 2018). "IGFs that are secreted from stromal cells can act on cancer cells via direct IGF-1R signaling, and together with hepatocyte growth factor/HGF, can phosphorylate Annexin A2/AnxA2, a protein that has a well-established role in invasion/metastasis." (PMID 29475434, 2018). "One of the effective ways to block signaling from IGF-1R in cancer cells is to identify the small molecules which can inhibit the tyrosine phosphorylation of its β subunit." (PMID 30213025, 2018). "The evidence that the IGF-axis plays a critical role in malignancy has led to an intensive effort to develop anti-cancer drugs that target the IGF-1R." (PMID 30478273, 2018). "In our study, we found that IGF-1 stimulated the phosphorylation of GSK-3β in PC12 cells, indicating that the inhibition of GSK-3β plays a positive role in promoting the development of cancer, at least in IGF-1R-mediated cancer." (PMID 30213025, 2018). "Cancer cells acquire resistance against EGFR inhibitor treatment via loss of IGFBP-3, which activates the IGF-1R signaling pathway." (PMID 29445126, 2018). "IGF-1R is also linked to the activation of Akt/mTOR signaling and activation of JNK in cancer cells." (PMID 30213025, 2018).
cancer (continued). "IGF-1/IGF-1R signaling is strongly dependent on nutrient availability and involves intensification of cancer cell proliferation, through the direct effects on PI3K/Akt signaling, and resistance to cell death imposed by chemotherapeutics and radiotherapy." (PMID 29868472, 2018). "Activation of IGF1-R can prevent cleavage of caspases in both cancer cells and fetal brain cells, preventing apoptosis." (PMID 30340501, 2018). "In line with the development of immunotherapeutic approaches in various cancer types, targeting the IGF1R signaling pathway in combination with immunotherapy should be investigated." (PMID 29922232, 2018). "After the failures of anti-IGF-1R trials in some cancer types, IR-A signaling has been postulated as one of the major mediators of resistance to anti-IGF-1R therapy." (PMID 30453495, 2018). "The IGF1R over-expression was observed in all cases, healthy, dysplastic and cancer tissue compared to WT tissue." (PMID 29662006, 2018). "This latter growth factor has a role in cancer progenitors’ biology due to its ability to activate high expression of IR-A and IGF-1R." (PMID 30513575, 2018). "A recent study has suggested an alternative approach, targeting both IGF-1R and IR degradation to treat cancers having IR/IGF-1R overactivation." (PMID 30453495, 2018). "Analysis of the esophageal tissue of WT females showed a significantly higher phosphorylation level of IGF1R in both dysplastic (7-fold higher) and cancer (2.2-fold higher) tissues compared to healthy tissue." (PMID 29662006, 2018). "This activation does not only provide survival signals for the fibroblasts, but also activates IGF-1R on cancer cells via IGF-1 that is secreted by fibroblasts and by pancreatic stellate cells (PaSCs) in response to Shh." (PMID 29475434, 2018). "The insulin-like growth factor (IGF) signaling system is a major arena of intragenomic conflict over embryonic growth between imprinted genes of maternal and paternal origin and the IGF type 1 receptor (IGF1R) promotes proliferation of many human cancers." (PMID 29644076, 2018). "IGF1R as well as EGFR signaling pathway plays a critical role in cancer cell survival, facilitating resistance to γ-radiation and anticancer drugs." (PMID 30013043, 2018). "In cancer cells, the biological response to insulin cannot be predicted only on the basis of the IR and IGF-1R expression levels." (PMID 30453495, 2018). "In contrast, inhibition of IGF-1R expression with the monoclonal antibody against IGF-1R, ganitumab, induces cytotoxicity of cancer cells." (PMID 30602706, 2018). "IGF-1 is a strong mitogen, which stimulates IGF-1R signaling and thus plays important roles in the occurrence and growth of several cancers." (PMID 30213025, 2018). "Several studies report that the enhanced activation of the IGF-1/IGF-1R signaling axis promotes cancer proliferation and survival." (PMID 30111747, 2018). "Previous studies have shown that activation of the IGF1R signaling pathway is involved in proliferation, survival, and metastasis of cancer cells." (PMID 29642855, 2018). "Focusing more on this phenomenon can help researchers to identifty novel therapy targets for dual inhibition IGF-1R signaling, and other signaling pathways, and thereby can create an oppurtunity for dual targeting of stroma and cancer cells." (PMID 29475434, 2018). "Both IGF1R and Src are frequently overexpressed in various types of human cancer, inversely correlated with patient survival, and known to crosstalk with each other." (PMID 29455661, 2018). "Analogous to MKR females, protein expression in esophageal tissue from MKR males showed a significant decrease of both IR and IGF1R expression in cancer compared with control tissue." (PMID 29662006, 2018).
cancer (continued). "Within the complex interplay between the IGF system and cancer, IGF-1R signaling is involved in the metabolic shift of transformed cells from an aerobic to an anaerobic production of ATP, known as the “Warburg effect”." (PMID 30111747, 2018). "IGFIR is a tyrosine kinase that was significantly higher in adenomatous polyps and carcinoma as compared with healthy controls, and a positive correlation was observed between serum IGF1 and mucosal IGF1R mRNA expression in the polyps." (PMID 29455652, 2018). "On the other hand, insulin-like growth factors activate the IGF-1R, make it over expressed in cancer cells, and then trigger a number of intracellular signaling cascades that enhance cell cycle progression and inhibit apoptosis." (PMID 28423026, 2017). "Previously, we demonstrated that glypican-3 (GPC3) is highly expressed in HCC, and that GPC3 induces oncogenicity and promotes the growth of cancer cells through IGF-1 receptor (IGF-1R)." (PMID 29113314, 2017). "The IGF1R is involved in both physiological and pathological activities and is usually overexpressed in most types of cancer." (PMID 28945762, 2017). "Insulin-like growth factor-1 receptor (IGF-1R) induces the common pathways for normal cell growth, as well as cancer development, suggesting that IGF-1R is a potential target for cancer therapy." (PMID 28427155, 2017). "Autophagy-disrupting agents can enhance the effect of IGF-1R inhibitors and will be a valuable complement to IGF-1R inhibitor-based therapies for cancers." (PMID 28046018, 2017). "IGF1R is dramatically overexpressed in various cancers and possess oncogenic properties through subsequently activating intracellular the PI3K and MAPK pathways, which promote cellular proliferation and metastasis." (PMID 27487126, 2017). "Dysregulation of receptor tyrosine kinases such as Vascular Endothelial Factor Receptor two and Insulin-like Growth Factor-1 Receptor can lead to cancer." (PMID 28537552, 2017). "Although treatment arm and cancer stage were strong prognostic factors, IGF1R and AREG status were also independent prognostic factors." (PMID 26884344, 2017). "Reciprocal activation has been observed between the IGF-1R and the AR signaling pathways, supporting the rationale of simultaneous inhibition in cancer treatment." (PMID 28447314, 2017). "Using cell fractionation, confocal microscopy and additional cellular and biochemical analyses, we and others have previously shown that IGF1R is present in the nucleus of breast and other cancer cell lines and tissues." (PMID 28945762, 2017). "As such, miR‐15b has been reported to regulate Wee1, Bcl‐2, cyclin E, cyclin D and/or IGF‐1R expression in several types of cancer, and many of these genes also play important roles in drug resistance and apoptosis resistance." (PMID 28145098, 2017). "IGF1R protein was expressed in cancer cells in the only two cases with IGF1R amplification; there was no positive staining in the remaining 39 samples (data not shown)." (PMID 27891760, 2017). "These three results all insignificantly described the curative effects, thus further study of IGF-1R inhibitors to treat cancer was needed." (PMID 28427155, 2017). "The vast majority of studies conducted to date on nuclear IGF1R translocation were carried out in cancer-derived cells." (PMID 28945762, 2017). "Recently, around 30 compounds targeting IGF‐1R have been tested in phase II/III clinical trials for the treatment of several types of cancer including ESCC." (PMID 28440057, 2017). "Insulin-like growth factor (IGF) signaling system which consisted of ligands (IGF-1 and IGF-2), growth factor receptors (IGF-1R, IGF-2R) and IGF binding proteins (IGFBPs 1-6), also has been implicated in the development, maintenance, and progression of cancer." (PMID 28460483, 2017).
cancer (continued). "In all, we suggest that some more frequently observed severe adverse events for specific cancer types should be paid adequate attention when using mono-anti-IGF-1R mAbs, and it was essential to choose the proper combination regimen to reduce AE-occurrences." (PMID 28427155, 2017). "Recent data suggest that insulin-like growth factor 1 receptor (IGF1R) exerts dominant control over PI3K signaling in human KRAS mutant cancers." (PMID 28152508, 2017). "IGF1R seems to be a promising target for cancer treatment and several strategies blocking IGF1R activity are undergoing clinical trials." (PMID 28793874, 2017). "In recent years, the IGF1R emerged as a promising therapeutic target in breast and other types of cancer." (PMID 28706506, 2017). "Given that IGF1R is a well-documented oncogenic factor in many different types of cancers, and therapeutically targeting its activity in isolation has proven to be unsuccessful, a better understanding of its signaling activity is certainly required." (PMID 29207959, 2017). "Three data from ongoing clinical trials (NCT00372996, 2015; NCT00887159, 2015; NCT00684983, 2016) also indicated insignificant cancer curative value of anti-IGF-1R agents." (PMID 28427155, 2017). "Of note, there is also mounting evidence for diverse IGF-1R-independent functions of IGFBPs with relevance to cancer." (PMID 28959684, 2017). "Patients with CRPCa and IGF-1R staining scores of 0–4, i.e. scores below median showed shorter cancer-specific survival than patients with staining scores of 6 and above; median survival was 2.5 versus 9.3 months (log-rank 11, P = 0.001, n = 15 vs. 32)." (PMID 28447314, 2017). "Together, these data demonstrate that the IGF1R/AKT1 signaling pathway significantly impacts the acquisition of chemoresistance in cancer cells." (PMID 28880250, 2017). "Empirical support to this view was provided by preclinical studies showing that IGF1R hyperactivation constitutes a fundamental prerequisite for cancer development." (PMID 28706506, 2017). "Most basic, clinical and epidemiological studies agree with the notion that constitutive activation of the IGF1R tyrosine kinase domain constitutes a relatively common event in cancer cells." (PMID 28706506, 2017). "Our analysis used up-to-date data to show the pessimistic result of anti-IGF-1R mAbs on cancer therapy." (PMID 28427155, 2017). "Although early phase clinical trials raised hope for the use of IGF1R-specific antibodies for cancer therapy, results from phase II–III trials of these agents in unselected patients have not demonstrated significant benefits in the clinic." (PMID 29099049, 2017). "Although studies in mouse cancer models were often supportive, interventions directed at inhibition of the IGF1R in man as a single therapy and in combination with chemotherapy have not shown efficacy." (PMID 28753127, 2017). "Numerous studies show the involvement of IGF1-R in tumorigenesis and development of cancer drug resistance." (PMID 29137221, 2017). "Several types of cancer cells are heavily dependent on IGF‐1R for survival, which has been demonstrated both in vivo and in vitro." (PMID 28112398, 2017). "Circulating insulin and IGF-1 primarily converge with intrinsic cancer cell metabolic processes via binding to their cell surface receptors, specifically insulin receptor (IR) and IGF-1R." (PMID 28959684, 2017). "Over the past few decades, findings regarding the role of the IGF1R in cancer have continued to accumulate." (PMID 27179633, 2016). "The converse scenario (i.e., that enhanced IGF1R gene expression in cancer is a consequence of the malignant phenotype) is, similarly, a biologically plausible theory that merits consideration." (PMID 27446805, 2016). "Inhibition of mTOR signaling often activates PI3Kinase/Akt pathway as a feedback mechanism in many cancers by up regulating insulin-like growth factor-1 receptor (IGF-IR) signaling." (PMID 27680387, 2016).
cancer (continued). "Recently, we and others demonstrated that the efficacy of targeting IGF1R alone in cancer is limited." (PMID 27179633, 2016). "The miRNA-99 family's modulation of the PI3K/mTOR signaling pathway and IGF-1R signaling have been observed in a number of cancers, supporting their role in modulating proliferation, migration, and apoptosis." (PMID 27840833, 2016). "Our results demonstrate that IGF1R-KD specifically in CD24+ cancer cells alters their morphology and phenotype and, more importantly, markedly inhibited their tumorigenic capacity." (PMID 27179633, 2016). "Differential interference contrast microscopy confirmed that the conjugated antibody reacted with IGF-1R on the surface of the cancer cells." (PMID 26731105, 2016). "In this study we demonstrate that downregulation of the IGF1R specifically in cancer cells expressing CD24 on the cell surface membrane affect both their morphology (from mesenchymal-like into epithelial-like morphology) and phenotype in vitro." (PMID 27179633, 2016). "Whereas CD24 can serve in certain cases as a marker for stemness, the IGF1R was found to play a crucial role in maintaining pluripotent properties of human embryonic stem cells; the self-renewal property of cancer stem cells." (PMID 27179633, 2016). "Insulin-like growth factor-1 receptor (IGF-1R) is involved in cancer cell metabolism, proliferation, differentiation, apoptosis, and carcinogenesis and chemoresistance." (PMID 26941789, 2016). "ACC is an endocrine tumor where the massive secretion of IGF2 acts in an auto/paracrine loop to sustain cancer cell proliferation, via activation of both insulin and IGF-1R pro-survival intracellular pathways." (PMID 27391065, 2016). "Meanwhile, MAPK1, AKT3 and IGF1R regulated by hsa-miR-4429 also participate in the Proteoglycans in cancer (FDR = 0.004268857), Rap1 signaling pathway (FDR = 0.018406673) and Ras signaling pathway (FDR = 0.024181237)." (PMID 26879603, 2016). "It processes many cancer-related proteins like IGF1R, the vascular endothelial growth factor C (VEGF-C) or the membrane-type 1 matrix metalloprotease (MT1-MMP)." (PMID 27572312, 2016). "As an anti-cancer target, the IGF1R axis has been studied in many clinical trials over the past years." (PMID 27285981, 2016). "We used the tail vein metastasis assay to determine the effect of IGF1R-KD in both subsets of cancer cells." (PMID 27179633, 2016). "The insulin-like growth factor (IGF) signaling system plays a critical role in tumorigenesis, highlighting the potential of targeting IGF-1R as an anti-cancer therapy." (PMID 27488947, 2016). "Given its strong pro-survival activity along with its universal expression in cancer cells, the IGF1R emerged in recent years as a promising therapeutic target in oncology." (PMID 27446805, 2016). "After incubation with the fluorophore-conjugated IGF-1R antibody, without permeation, multiple fluorescent foci were visualized on the membrane of Panc-1 and BxPC-3 cells under fluorescence microscopy confirming the expression of IGF-1R on cancer cells." (PMID 26919100, 2016). "FACS analysis of cancer cells dissociated from CD24+ control and IGF1R-KD tumors, revealed that IGF1R is essential for the maintenance of stem/progenitors-like cancer cells that fuel the cancer process as recently described." (PMID 27179633, 2016). "Increased signaling through IR and IGF-1R, leading to activation of PI3K and MAPK kinase pathways, is associated with increased proliferation in cancer." (PMID 27840833, 2016). "Soon after our original study, several others have reported nuclear IGF-1R (nIGF-1R) as well, and some of them have demonstrated a prognostic value of nIGF-1R expression in cancer." (PMID 27275536, 2016). "On the other hand, the central node Akt of the IR/IGF-1R downstream pathways seems to be mostly effected and remains as a promising target for further cancer therapeutics." (PMID 27849005, 2016).